BANCR (BRAF-activated non-protein coding RNA)
Diseases named in the same sentence as BANCR in open-access papers (continued):
Sharing a sentence is not in itself a finding about the gene and the disease.
eosinophilic esophagitis (2 papers, 2017 to 2018). Eosinophilic esophagitis (EoE) is a chronic, allergic disease of the esophagus characterized clinically by symptoms of esophageal dysfunction (including vomiting, dysphagia, feeding disorders, food impaction and abdominal pain) which persist after treatment with proton pump inhibitors (PPIs). "The lncRNA BANCR was upregulated in eosinophilic esophagitis, which is another allergic inflammatory disorder, and was induced in IL-13 that treated primary esophageal epithelial cells." (PMID 28057064, 2017).
renal carcinoma (2 papers, 2018 to 2020). A carcinoma arising from the epithelium of the renal parenchyma or the renal pelvis. "The results indicated that BANCR expression was markedly down-regulated in renal cancer tissues compared to normal renal tissues (p < 0.01)." (PMID 30200918, 2018). "Expression of BANCR in TCGA renal cancer data sets was analyzed." (PMID 30200918, 2018). "BANCR was downregulated in renal cancer according to TCGA data sets." (PMID 30200918, 2018). "We analyzed the expression of BANCR in TCGA renal cancer data sets." (PMID 30200918, 2018).
lung adenocarcinoma (1 paper, 2014). A carcinoma that arises from the lung and is characterized by the presence of malignant glandular epithelial cells. "Furthermore, BANCR suppresses NSCLC cell metastasis in vivo: in fact, nude mice injected with BANCR-overexpressing lung adenocarcinoma cells display a reduction of the number of metastatic nodules, confirming the potential tumor-suppressing role of BANCR." (PMID 25428918, 2014).
melanocytic nevus (1 paper, 2014). A neoplasm composed of melanocytes that usually appears as a dark spot on the skin. "The total five cell lines showed a notable overexpression of BANCR compared to the control skin tissue pooled from 3 controls with melanocytic nevus (P<0.001)." (PMID 24967732, 2014).
ocular toxoplasmosis (1 paper, 2019). Ocular toxoplasmosis is an infection in the eye caused by the parasite, Toxoplasm a gondii. "In our results—obtained in human retinal Müller cells, which have direct relevance to ocular toxoplasmosis—LINC01105, BANCR, MIR17HG, MIR155HG, lnc-SGK1, MEG3, KCNQ1OT1, NEAT1, NeST, and MALAT1 were the most dysregulated lncRNAs with known immunologic activities." (PMID 31547203, 2019).
renal cell carcinoma (1 paper, 2021). "Similarly, BANCR levels have been shown to be reduced in renal cell carcinoma samples compared with neighboring unaffected kidney samples in correlation with poor prognosis implying the appropriateness of BANCR as a new prognostic marker in renal cell carcinoma." (PMID 34409032, 2021).
tumor (56 papers, 2014 to 2025). "The pooled OR showed a strong association between high BANCR expression and advanced tumor stage (HR = 2.39, 95% CI: 1.26–4.53, P < 0.001)." (PMID 32907530, 2020). "Increased expression of lncRNA BANCR was positively associated with tumor size, choroidal invasion, and optic nerve invasion." (PMID 29212285, 2017). "High BANCR levels were positively associated with clinical stage, tumor depth, lymph node and distant metastasis, and poor prognosis." (PMID 26758762, 2016). "Down-regulation of BANCR is associated with larger tumour size, advanced pathology, metastasis distance and shorter overall survival time of patients diagnosed with NSCLC." (PMID 25297942, 2014). "In addition, OE of BANCR inhibited the growth of ccRCC cells in vivo, and G6PD was implicated in BANCR-mediated tumor suppression." (PMID 39894218, 2025). "Although BANCR is an important lncRNA associated with cancer, its expression patterns vary among various types of cancer, and its function exhibits a dual nature, acting both as a tumor suppressor and a tumor promoter." (PMID 39894218, 2025). "Patients with BRAF V600E mutation, over-expression of BANCR and down-regulation of miR-9 have been shown to need earlier surgical management particularly total thyroidectomy in primary surgery in order to decrease tumor recurrence." (PMID 34409032, 2021). "Notably, expression levels of BANCR can be used for establishment of personalized methods of cancer treatment and stratification of patients based on the risk of tumor recurrence." (PMID 34409032, 2021). "In addition, BANCR and miR-9 expression in adjacent normal tissue was also associated with tumor location, size, and multifocality." (PMID 32593310, 2020). "Moreover, BANCR was associated with large tumor size, distant metastasis, and advanced clinical stage, and was an independent predictor of poor survival rate." (PMID 31850493, 2020). "Moreover, CSE1L expression was positively associated with BANCR expression in 32 cases of CRC tumor tissues." (PMID 30144787, 2018). "Moreover, the aberrant expression of BANCR was positively associated with clinical stage, tumor depth, lymph node metastasis, and distant metastasis, and was an independent prognostic factor for GC/NSCLC in survival analysis." (PMID 27686732, 2016). "Additionally, reduced BANCR expression was associated with larger tumor size, advanced pathological stage, metastasis distance, and shorter overall survival of NSCLC patients." (PMID 24655544, 2014). "Moreover, CSE1L level was positively associated with BANCR level in CRC tumor tissues." (PMID 30144787, 2018). "To validate these predictions, we performed RNA FISH testing in ccRCC cell lines and human ccRCC tumor tissues to examine the interaction between BANCR and G6PD." (PMID 39894218, 2025). "To further validate the effect of BANCR on the in vivo growth of ccRCC cells, we conducted subcutaneous tumor assays." (PMID 39894218, 2025). "The results showed that the tumor volume and weight formed by the BANCR-knockdown 786-O cells were markedly larger than those formed by the negative control cells." (PMID 39894218, 2025). "Its regulatory direction exhibits tissue specificity, and BANCR acts as either an oncogene or a tumor suppressor gene in different cancers." (PMID 39894218, 2025). "Overall, these results confirmed that G6PD was a pivotal downstream target of BANCR, playing a significant role in the tumor-suppressive function mediated by BANCR in ccRCC." (PMID 39894218, 2025). "In vivo models further confirmed that BANCR enhances endometrial cell survival and tumor development through this pathway." (PMID 40364006, 2025). "This was confirmed in a xenograft model of thyroid cancer, whereby luteolin treatment at 50 mg/kg decreased tumor growth in vivo, and this anti-tumor effect was abolished by BANCR overexpression." (PMID 41226537, 2025).
tumor (continued). "As a malignant tumor-related lncRNA, BANCR regulates multiple signaling pathways through multiple links and plays a variety of roles in tumor cell proliferation, survival, migration, tumorigenesis, and metastasis." (PMID 37998732, 2023). "In order to explore the underlying mechanism by which BANCR is upregulated in PC, the relationship between BANCR expression and BANCR m6A modification in PC tumor tissues was detected by RT-qPCR and MeRIP-PCR." (PMID 37998732, 2023). "In studies on the lncRNA BANCR, knockdown of BANCR significantly reduced tumor growth in BALB/c mouse CRC models." (PMID 38092752, 2023). "LncRNA BANCR (also known as LINC00586) is overexpressed in HCC and linked to larger tumor volume, later TNM stage and shorter overall survival." (PMID 37837401, 2023). "We analyzed the correlations between the expression levels of BANCR in PC tumor tissues and patients’ clinicopathological parameters." (PMID 37998732, 2023). "The level of BANCR m6A was higher in PC tumor tissues with highly expressed BANCR compared to lowly expressed BANCR." (PMID 37998732, 2023). "BANCR is closely related to the status of tumor activity, suggesting that it has certain potential for early diagnosis and evaluation of ESCC." (PMID 35241975, 2022). "In direct conflict with the initial studies, researchers using an in vivo model of BANCR overexpression in CRC found that the overexpression of BANCR inhibits tumor growth." (PMID 36010859, 2022). "BANCR silencing downregulates MAPK signaling inhibits tumor growth and migration by upregulating the chemokine CXCL11." (PMID 35159386, 2022). "After the patient’s tumor is removed, the expression level of BANCR returns to normal, and as the disease progresses, the expression level of BANCR gradually increases, which has certain potential for early diagnosis and evaluation of ESCC." (PMID 35241975, 2022). "Conversely, another group using a similar in vivo model found that silencing of BANCR inhibits tumor growth, in line with the findings of initial studies." (PMID 36010859, 2022). "BANCR exerts its effects via modulating some tumor-related signaling pathways particularly MAPK and other regulatory mechanisms such as sponging microRNAs (miRNAs)." (PMID 34409032, 2021). "Tumor suppressor role of BANCR is mediated through modulation of p38 MAPK, p21, ERK, PI3K-Akt, and Wnt pathways." (PMID 34409032, 2021). "In vivo studies in animal models have also confirmed the role of BANCR deregulation in tumor progression." (PMID 34409032, 2021). "The consequences of BANCR over-expression and down-regulation on tumor growth have been appraised in vivo." (PMID 34409032, 2021). "For instance, while a study in the xenograft model of thyroid cancer has shown the impact of BANCR up-regulation on enhancement of tumor growth, another study has reported the opposite results." (PMID 34409032, 2021). "BANCR exerts its effects via modulating some tumor-related signaling pathways particularly MAPK and other regulatory mechanisms such as sponging miRNAs." (PMID 34409032, 2021). "For example, the expression of lncRNA BRAF-Activated Non-Protein Coding RNA (BANCR) significantly decreases in NSCLC tumor tissues, and the ectopic expression of BANCR inhibits the metastatic abilities of SPC-A1 and A549 cells." (PMID 34692550, 2021). "Intraperitoneal injection of rutin and SO alone for 14 days inhibited tumor growth, BANCR, and OLR1 levels, while promoted miRNA-590-5P expression." (PMID 34512168, 2021). "BRAF-activated noncoding RNA (BANCR) is aberrantly expressed in various tumor tissues and has been confirmed to function as a tumor suppressor or oncogene in many types of cancers." (PMID 32907530, 2020). "It has been reported that BANCR has a tumor suppressing effect in liver and bladder cancers, while it acts as an oncogene in gastric, colorectal, and lung cancers." (PMID 32596158, 2020). "BANCR has both carcinogenic and tumor suppressing effects, and can play different roles in different tumors." (PMID 32596158, 2020).
tumor (continued). "Patients with higher BANCR expression in adjacent normal tissue had a lower frequency of bilateral tumors and multifocality, and a larger tumor as compared to those with lower BANCR levels." (PMID 32593310, 2020). "First identified as an oncogene in melanoma for its ability to activate MAPK pathway and induce tumor cell migration and proliferation, BANCR has also been reported as tumor suppressor in NSCLC for its role in epithelial-mesenchymal transition (EMT)." (PMID 33142861, 2020). "In fact, knocked down BANCR limited tumor invasion, metastatic capacity, and proliferation, indicating its potential usefulness as a therapeutic target for Rb." (PMID 31798638, 2019). "Next, mice xenograft models of CRC were established to explore the influence of BANCR knockdown on tumor growth and ADR sensitivity." (PMID 30144787, 2018). "In this study, we firstly demonstrated that BANCR and CSE1L expressions were both up-regulated in CRC tumor tissues, and CSE1L expression was positively associated with BANCR expression and clinicopathological factors of CRC." (PMID 30144787, 2018). "That is to say, BANCR knockdown inhibited tumor growth and induced ADR sensitivity in CRC possibly by modulating miR-203/CSE1L axis." (PMID 30144787, 2018). "Our in vitro and in vivo data show that BANCR acts as a tumor suppressor that inhibits tumor growth and metastasis, in line with the clinicopathological data." (PMID 27462868, 2017). "In this regard, expression of BANCR is reduced in patient tumours, and re-expression of BANCR levels induced E-cadherin expression, along with decreased N-cadherin, Vimentin, SNAIL1, and SNAIL2 expression." (PMID 28430163, 2017). "BANCR is frequently overexpressed in the multiple tumor tissues, playing carcinogenic roles in the progression of cancers." (PMID 29212285, 2017). "Our results show that BANCR overexpression inhibits cell proliferation, migration and invasion while inducing tumor cell apoptosis." (PMID 27462868, 2017). "Our results demonstrated that higher BANCR expression predicted higher tumor stage in GI cancer patients in China." (PMID 28009984, 2017). "Decreased BANCR levels correlate with tumor size, the presence of multifocal lesions and advanced PTC stage." (PMID 27462868, 2017). "Higher BANCR expression was also associated with LNM (OR = 3.41, 95%CI: 1.82–6.37, P = 0.0001), DM (OR = 2.98, 95% CI: 1.76–5.07, P < 0.0001), and tumor stage (OR = 3.11, 95% CI:1.89–5.12, P < 0.00001) in these patients." (PMID 28009984, 2017). "In conclusion, high BANCR expression was associated with LNM, DM, advanced tumor stage, and poor OS in multiple GI cancers." (PMID 28009984, 2017). "For example, lncRNA BANCR functions as a tumor suppressor in NSCLC, whereas HOTAIR and MALAT1 promote oncogenic functions in NSCLC." (PMID 29228680, 2017). "The relationship between BANCR expression and tumor stage was analyzed in 692 patients from eight eligible studies." (PMID 28009984, 2017). "And there are several difficult problems should be solved to utilize BANCR as a tumor marker for cancer diagnosis and treatment." (PMID 29212285, 2017). "Our results show that downregulation of BANCR expression correlates with tumor size (P < 0.05), the presence of multifocal lesions (P < 0.05) and advanced pathological stage (P < 0.05) in PTC tissues." (PMID 27462868, 2017). "Dysregulation of BANCR is related with the progression of cancers, affecting the tumor size, clinical stage and TNM stage of cancer patients." (PMID 29212285, 2017). "Clinicopathologic analysis revealed that high BANCR expression correlated with high tumor grade, large tumor size, venous infiltration, advanced tumor, node, and metastasis (TNM) stage, and shorter overall survival." (PMID 26758762, 2016). "In retinoblastoma tissues, high BANCR expression was correlated with tumor size and invasion of choroid and optic nerve." (PMID 27686732, 2016).
tumor (continued). "Although our findings suggest that BANCR plays a role in the oncogenic process, tumor growth and progression, further studies in larger samples with a better distribution of each stage are required." (PMID 25928067, 2015). "Larger tumors, which represent a higher tumor burden, or more advanced tumors had lower BANCR expression." (PMID 25928067, 2015). "The results showed that the levels of BANCR expression in tumor tissues formed from pCDNA-BANCR cells were higher than those of the tumors formed in the control group (p < 0.01)." (PMID 25928067, 2015). "Clinicopathological factors were analysed between the two groups and the high-BANCR expression group showed more advanced LN metastasis and tumour stage than the low-BANCR expression group (P<0.05)." (PMID 25013510, 2014). "BANCR (BRAF activated non-coding RNA) functions as a tumour-suppressor lncRNA and can regulate cell proliferation by mediating cell-growth arrest and inhibiting cell invasion, thereby reducing the incidence of malignancy." (PMID 25297942, 2014). "The qPCR results demonstrated that BANCR expression was significantly higher in the tumour tissues than in the adjacent normal tissues (P<0.05)." (PMID 25013510, 2014). "According to relative BANCR expression in tumor tissues, the 113 NSCLC patients were classified into two groups: the high BANCR group (n = 53, fold-change ≤ 4); and the low BANCR group (n = 60, fold-change ≥4)." (PMID 24655544, 2014). "Specifically, BANCR expression was significantly lower at the later stages of tumor development, and in tumors that had undergone extensive metastasis." (PMID 24655544, 2014). "The qPCR showed that BANCR was upregulated in CRC tumour tissues compared with adjacent normal tissues." (PMID 25013510, 2014). "In the present study, it was found that BANCR expression levels were upregulated in five out of six PTC tumor tissues compared with their adjacent normal tissues." (PMID 25289082, 2014). "BANCR knockdown induced by shRNA transfection significantly inhibited proliferation of tumor cells and inactivated MAPK pathway, especially by silencing the ERK1/2 and JNK component." (PMID 24967732, 2014). "The RT-PCR results showed that BANCR expression was significantly higher in five out of six of the tumor tissues compared with the adjacent normal tissues." (PMID 25289082, 2014). "BANCR expression was significantly decreased in 113 NSCLC tumor tissues compared with normal tissues." (PMID 24655544, 2014). "BANCR expression levels in NSCLC were significantly correlated with tumor size (p = 0.001), advanced pathological stage (p < 0.001), and lymph node metastasis (p = 0.001)." (PMID 24655544, 2014). "The 60 patients with CRC were divided into high- (n=18) and low-BANCR expression (n=42) groups according to the mean value of the expression levels of BANCR in tumour tissues." (PMID 25013510, 2014). "The quantitative polymerase chain reaction results showed that BANCR was frequently overexpressed in cancer tissues and this overexpression was found to significantly correlate with lymph node metastasis and tumour stage." (PMID 25013510, 2014). "By tumorigenicity assay in BALB/c nude mice, we further found that BANCR knockdown inhibited tumor growth in vivo." (PMID 24967732, 2014). "The accumulated evidence strongly suggests that BANCR may exert its tumor-suppressive effect on ccRCC through interaction with G6PD." (PMID 39894218, 2025). "The BANCR levels in each group of tumors were negatively correlated with tumor size." (PMID 39894218, 2025). "Furthermore, the tumor size, bilateral tumor site, multifocality, extracapsular invasion, and lateral LNM were strongly correlated with the BRAFV600E mutation and the BANCR (BRAF-activated non-coding RNA) and miR-9 expression." (PMID 39057172, 2024). "As a result, the expression levels of target miRs in each tissue may define BANCR’s oncogenic or tumor suppressive activity." (PMID 38137560, 2023).